FAM20C (FAM20C golgi associated secretory pathway kinase)
Diseases named in the same sentence as FAM20C in open-access papers (continued):
Sharing a sentence is not in itself a finding about the gene and the disease.
heart disease (3 papers, 2018 to 2021). "Fam20C’s potential role in cardiac function was highlighted by the identification of a heart disease-associated polymorphism in luminal SR resident histidine-rich Ca2+-binding protein (HRC)." (PMID 30520731, 2018). "Besides FGF23, which contributes directly to cardiovascular problems in patients, various other substrates of Fam20C have been implicated in heart disease." (PMID 33759783, 2021). "In addition, Stim1-Ser88Gly, a mutation recently discovered in a patient with heart disease (see discussion), is less robustly phosphorylated than Stim1-WT in vitro and in cells, suggesting that Fam20C phosphorylates Stim1-Ser88." (PMID 30520731, 2018). "In addition, a recently discovered Stim1-S88G substitution (within an SxE site) was found in a patient with heart disease and the substitution, which precludes Fam20C phosphorylation, was shown to alter Ca2+ signaling." (PMID 33759783, 2021). "Indeed, activators of Fam20C may benefit nonlethal Raine patients as well as protect against heart disease and other potential systemic health issues." (PMID 33759783, 2021).
metabolic disease (2 papers, 2024 to 2025). A congenital disorder (due to inherited enzyme abnormality) or acquired (due to failure of a metabolically important organ) disorder resulting from an abnormal metabolic process. "Future research is crucial to further elucidate the precise molecular targets of FAM20C in adipocytes and to translate these findings into effective therapies for metabolic diseases." (PMID 41148235, 2025). "Further investigation into these pathways could reveal additional mechanisms through which FAM20C exacerbates metabolic disease." (PMID 41148235, 2025). "However, the role of FAM20C in metabolic diseases and tissue growth, such as in adipose tissue, is understudied in comparison with other tissues and cell types." (PMID 39532808, 2024).
cardiovascular diseases (1 paper, 2025). "In addition, FAM20C has been found to be associated with the occurrence and development of certain cardiovascular diseases and endocrine metabolism disorders." (PMID 39790934, 2025).
neurodevelopmental disorder (1 paper, 2026). A behavioral and cognitive disorder with onset during the developmental period that involves impaired or aberrant development of intellectual, motor, or social functions. "In this study, we concentrated on the implications of FAM20C for neurodevelopmental disorders within HIBD." (PMID 40511628, 2026).
neurological disorders (1 paper, 2026). "Elucidating the interaction mechanism between FAM20C and ADAR, SAFB and DAGLA holds crucial implications for understanding both the physiological roles of FAM20C in the nervous system and its pathological contributions to neurological disorders." (PMID 40511628, 2026).
skeletal dysplasia (1 paper, 2019). Any Mendelian diseases that affects growth and development of the skeleton. "Importantly, skeletal phenotypes were described for Fam20c (non-lethal Raine syndrome), Lrrk1 (osteosclerotic metaphyseal dysplasia), Pappa2 (short stature), Sfrp4 (Pyle's disease), and Slc10a7 (skeletal dysplasia) prior to knowledge of the human skeletal dysplasias when mutated in humans." (PMID 32117046, 2019).
FAM20C also shares sentences with these, for which no sentence is quoted: osteosarcoma (5 papers); autosomal dominant hypophosphatemic rickets (4); atherosclerosis (2); breast invasive carcinoma (2); colorectal cancer (2); osteomalacia (2); skeletal disease (2); type 2 diabetes (2); X-linked dominant hypophosphatemic rickets (2); Alzheimer disease (1); Caffey disease (1); calcification (1); cardiac arrhythmia (1); cervical squamous cell carcinoma (1); chronic kidney disease (1); colon adenocarcinoma (1); depression (1); desmosterolosis (1); diastolic heart failure (1); endocrine disorders (1); genetic disorder (1); gingival fibromatosis (1); gingival hyperplasia (1); Glucose intolerance (1); Hepatic steatosis (1); hereditary hypophosphatemic rickets (1); Hyperglycemia (1); Hyperinsulinemia (1); Intellectual disability (1); kidney chromophobe (1).
A further 16 diseases each share a sentence with FAM20C in 1 paper.